CRP (C-reactive protein)
Diseases named in the same sentence as CRP in open-access papers (continued):
Sharing a sentence is not in itself a finding about the gene and the disease.
colitis (continued). "In this analysis of LUCENT-1 data, the univariable analysis identified left-sided colitis/proctitis, lower fCal level, lower CRP level, baseline MMS, lower ES, lower SF subscore, and no prior biologic or tofacitinib failure as candidate prognostic factors for patients achieving DC at W12." (PMID 40651005, 2025). "These measurements include inflammatory biomarkers (eg, C-reactive protein [CRP] and fecal calprotectin [FCP]) and activity indices assessed by the clinician (eg, the Harvey-Bradshaw Index [HBI],22 the CD Activity Index [CDAI],23 and the Simple Clinical Colitis Activity Index [SCCAI]24)." (PMID 40795293, 2025). "Moreover, the FC, ESR, and CRP were significantly higher in patients with MC than those without colitis." (PMID 39451656, 2024). "The discordance between the CRP and albumin and the UCEIS score within the subset of patients who underwent sigmoidoscopy further supports the finding that traditional biochemical markers used in idiopathic IBD are of limited use in the assessment of irAE colitis." (PMID 32418993, 2020). "On the other hand, CRP and Lcn-2 were not always altered between these different colitis models." (PMID 28566745, 2017). "Of note, log(fecal calprotectin) correlated with colitis activity much better than serum C-reactive protein (whether or not log-transformed): this is likely to reflect the fact that patients with CGD can have many other causes of systemic inflammation and concurs with another recent study." (PMID 31172380, 2019). "The methylation level of RUNX3 P2 did not correlate with age, sex, nutritional status, CRP, albumin, PUCAI, or the extent of colitis (Paris E1–E4)." (PMID 36140736, 2022). "However, these factors are not specific to ICI-induced colitis, and moreover, it has been reported that the biochemical parameters, including CRP, albumin, and hemoglobin, did not correlate with the severity of ICI-induced colitis." (PMID 38461170, 2024). "Whereas the current biomarkers, CRP and Lcn-2, did not discriminate between the DSS-induced and IL10−/− mouse models of colitis, our signature could make this distinction." (PMID 28566745, 2017).
osteoporosis (104 papers, 2006 to 2026). A condition of reduced bone mass, with decreased cortical thickness and a decrease in the number and size of the trabeculae of cancellous bone (but normal chemical composition), resulting in increased fracture incidence. "This study, based on a large cohort of 468 patients with osteoporosis complicated by DF, systematically evaluated the association between Hs-CRP and the risk of all-cause mortality." (PMID 41601759, 2026). "Association between Hs-CRP and all-cause mortality in patients with osteoporosis complicated by diabetic foot." (PMID 41601759, 2026). "Multivariate subgroup association between Hs-CRP and all-cause mortality in patients with osteoporosis complicated by diabetic foot." (PMID 41601759, 2026). "While inflammatory indices such as NLR and CRP have shown reproducible associations with osteoporosis across cohorts in postmenopausal women, the contribution of basophils appears limited." (PMID 40979723, 2025). "The logistic regression analysis adjusted for the confounders showed that only the elevation of hs-CRP had a significant effect on the risk of osteoporosis (OR (95 % CI):42.41 (12.66–142.3), p < 0.001)." (PMID 39263180, 2024). "Nonetheless, there was a notable increase in the risk of osteoporosis when the hs-CRP levels were elevated (OR (95 % CI) = 42.41 (12.66–142.3), p < 0.001)." (PMID 39263180, 2024). "A study has shown that the inflammatory marker C-reactive protein is also associated with frailty and osteoporosis." (PMID 38982542, 2024). "While the associations of low BMI and persistent CRP with osteoporosis have been reported in the general population, studies looking into the impact of persistent inflammation and the pathogenesis of osteoporosis in IBD are required." (PMID 39275145, 2024). "The Geelong Osteoporosis study reported that as CRP increased with each SD, fracture risk was significantly and independently increased by 24–32%29." (PMID 37393312, 2023). "The second is that the potential risk factors for osteoporosis were age > 60 years, BMI <18 kg/m2, history of exacerbation in the previous year, and a CRP level > 0.6 mg/L." (PMID 37614952, 2023). "Higher CRP levels (>3 mg/L) emerged to be the highest independent predictor, bearers of which had 2.77 odds of higher risk of osteoporosis (OR 2.77 95%CI: 2.18–3.56, p = 0.008) than those who had lower levels of CRP." (PMID 35270692, 2022). "It is also necessary to investigate associations among inflammatory markers (IL-6, TNF-α, CRP), myosteatosis, blood lipid levels, adiposity, osteoporosis or osteopenia, bone demineralization and other comorbidities." (PMID 35330186, 2022). "This is endorsed by the present study, where higher CRP levels have emerged to be the strongest risk factor for osteoporosis and osteopenia." (PMID 35270692, 2022). "Other studies suggest that cystatin C can also cause an inflammatory response and increase C-reactive protein indirectly through a chronic inflammatory response to participate in the formation of osteoporosis." (PMID 35646051, 2022). "Human leukocyte antigen-B27 (HLA-B27) positivity (OR 5.3, CI 1.07–15.3, p = 0.046), CRP level (OR 1.67, CI 0.13–0.96, p = 0.041), and use of glucocorticoids (OR 6.02, CI 1.36–26.6, p = 0.018) were associated with osteoporosis based on the WHO criteria." (PMID 35628957, 2022). "Higher CRP levels (>3 mg/L) emerged to be the most significant univariable marker, which tripled the risk of osteoporosis (OR 3.28 95%CI: 2.65–4.22, p < 0.001) and osteopenia (OR 2.13 95%CI: 1.51–2.84, p = 0.005)." (PMID 35270692, 2022). "Pasco’s study on osteoporosis found that the risk of fracture increased 24-32% for each SD increase in CRP levels in older women." (PMID 35432213, 2022). "In the Geelong Osteoporosis study, fracture risk increased by 24–32% for each SD increase in CRP independently of BMD, prevalent vertebral fractures and bone turnover parameters." (PMID 32158491, 2020).
osteoporosis (continued). "In the first step all parameters associated with osteoporosis (δ44/42CaBlood, δ44/42CaUrine, CRP, XTX, CTX/P1NP) were entered into the statistical model." (PMID 30997369, 2019). "Using logistic regression, the associations between osteoporosis and age, gender, BMI, fibroscan score, CRP level, and etiology of liver cirrhosis were analyzed, taking the patients with normal BMD and osteopenia as the reference." (PMID 29768330, 2018). "The total prevalence of osteoporosis and osteopenia in male Taiwanese COPD patients is higher than that in age-matched male subjects and increased CRP level, which indicated systemic inflammation is an independent risk factor for osteoporosis development." (PMID 29340241, 2018). "The CRP in Bone Loss and Osteoporosis group was significantly increased which demonstrated that osteopenia or osteoporosis was associated with an inflammatory response." (PMID 28620614, 2017). "Association between serum 25-hydroxyvitamin D and C-reactive protein in subjects with data on osteoporosis available." (PMID 26147588, 2015). "IL-18, IL-6 and hs-CRP are risk factors for trabecular bone destruction in osteoporosis patients." (PMID 31258577, 2019). "Binary logistic regression analysis for factors including age, BMI, creatinine, hs-CRP, smoking, steroid use, and forced expiratory volume in one second (FEV1) revealed that an hs-CRP level ≥5 and decreased creatinine level were independent risk factors for osteoporosis in COPD patients." (PMID 29340241, 2018). "Moreover, studies have shown an association of CRP with the pathogenesis of osteoporosis in the general population, and the levels of inflammatory factors such as hs-CRP were detected to be increased in osteoporosis patients." (PMID 39275145, 2024). "This prompts us to suggest a thorough osteoporosis check-up in patients with high CRP, LN, or U1-RNP-antibodies." (PMID 40722203, 2025). "C-reactive protein (CRP), an acute-phase reactant, is a well-established systemic inflammation marker and has been associated with osteoporosis and fractures in epidemiological studies." (PMID 41009701, 2025). "To assess the diagnostic accuracy of hs-CRP, TNF-α, and IL-6 compared to the DXA standard method for osteoporosis, we employed the ROC curve." (PMID 39263180, 2024). "A genetic association study identified SERPINA1 as a shared genomic region for C-reactive protein and osteoporosis." (PMID 39136019, 2024). "In geriatric dentistry, biomarkers such as osteopontin and C-reactive protein(CRP) are additionally employed to track the progression of systemic illnesses like osteoporosis and other age-related disordersaffecting dental health." (PMID 40230914, 2024). "The mean CRP level was significantly higher in the osteoporosis group, 4.78 ± 1.97 mg/L than in the osteopenia group, 1.62 ± 1.12 mg/L and the normal group, 0.92 ± 1.33 mg/L (p = 0.047)." (PMID 37614952, 2023). "Advanced age, lower body mass index (BMI), history of exacerbation in the previous year, and high CRP levels were significant predictors of osteoporosis." (PMID 37614952, 2023). "Several immunological and inflammatory illnesses in healthy people have shown a link between bone mineral density and circulating high sensitivity (hs) CRP levels, implying a connection between osteoporosis and subclinical systemic inflammation." (PMID 37371781, 2023). "A higher BMI protects against the risk of osteoporosis and osteopenia, whereas a higher SBP and higher levels of plasma CRP and TG along with poor sleep independently enhance the risk of osteoporosis and osteopenia in postmenopausal women of Punjab, India." (PMID 35270692, 2022). "In our data, menopause, ESR, CRP level, HLA-B27 positivity, glucocorticoid use, and PPI use were associated with an increased prevalence of osteoporosis and a high risk of osteoporotic fractures." (PMID 35628957, 2022).
osteoporosis (continued). "In the clinical chapters, it is suggested that chronic inflammation reduces BMD and higher levels of the inflammatory marker CRP is inversely associated with BMD and, hence, is directly associated with the risk of osteoporosis and fractures." (PMID 35270692, 2022). "At the time of diagnosis, AS patients were more likely to have osteoporosis of the spine (p = 0.021) and elevated CRP (p = 0.022) and were HLA-B27 positive (p = 0.030) when compared to nr-axSpA patients." (PMID 33611647, 2021). "Blood test abnormalities, such as serum ALP, phosphorus, ESR, and CRP levels, in patients with SpA/AS with long disease duration can differ from those of early-stage patients, as the former can develop osteoporosis." (PMID 34095182, 2021). "Meanwhile CRP levels were significantly lower in women with osteoporosis (P = 0.040) than the osteopenic and healthy groups." (PMID 31333751, 2019). "Among COPD patients, patients with osteoporosis had lower BMI, body weight, waist circumference, and triglyceride level but higher hs-CRP level, and tended to have lower creatinine level." (PMID 29340241, 2018). "The patients with osteoporosis tended to have greater age (P < .001), greater fibroscan score (P < .05), and higher CRP level (P < .05)." (PMID 29768330, 2018). "In this study, we included groups of human CRP transgenic mice to investigate the role of CRP in the development of osteoporosis in type 2 DM." (PMID 27283954, 2016). "Positive correlations between osteoporosis and C-reactive protein (CRP), a marker of active inflammation, have been observed, although not always confirmed, in a number of epidemiologic studies." (PMID 20682035, 2010). "Interestingly, in the Framingham Osteoporosis Study, a relationship between CRP (an acute phase inflammatory marker downstream of IL-6) and higher femoral neck aBMD was observed in postmenopausal women using menopausal hormone therapy." (PMID 40329072, 2025). "However, as the magnitude is too low to be biologically meaningful, significant caution should be taken in interpreting the clinical significance and application of serum C-reactive protein as a biomarker for osteoporosis." (PMID 37824509, 2023). "Furthermore, several epidemiological studies have shown positive correlations between osteoporosis and C-reactive protein (CRP) which is a marker of active inflammation." (PMID 31849841, 2019). "However, compared with Normal group, the age, years of menopause, BMI, and CRP of Osteoporosis group were significant differences (p < 0.05)." (PMID 28620614, 2017). "Finally, C-reactive protein, which increases during systemic inflammation, is elevated in both osteoporosis and migraine." (PMID 27610297, 2016). "We assessed whether there was a relationship between the extent of osteoporosis and biomarkers of disease activity including serum CRP concentration, DAS28, CDAI, SDAI, MHAQ score and the Steinbrocker classification." (PMID 26420629, 2015). "In addition, chemerin serum levels were reduced in women with osteoporosis, while c-reactive protein levels were increased, suggesting that adipokines, irisin and chemerin, may help to reduce the pathogenesis of osteoporosis." (PMID 34502045, 2021). "Therefore, this study primarily aimed to investigate risk factors for osteoporosis, particularly whether increased CRP is a predictor for osteoporosis development in male Taiwanese COPD patients since it is a common and available test in the hospital." (PMID 29340241, 2018). "Besides, serum iron accumulation may also be one of the important factors leading to inflammatory response in patients with osteoporosis, as CRP increased with the rise of Fer." (PMID 28620614, 2017). "Whereas previous work suggests that osteoporosis is linked to inflammation, it is not yet clear whether higher CRP levels are associated with bone loss." (PMID 26940634, 2016). "The results hardly changed when CRP, ESR and use of treatment for osteoporosis were included in the regression models." (PMID 25885788, 2015).
osteoporosis (continued). "Of those, only 11 factors (male sex, CCI, current smoking, bisphosphonate use, osteoporosis, BMD total hip and total body, circulating CRP and ALT, glomerular filtration rate, and educational level) were moderately correlated (|r| > 0.3) with either of the two principal components." (PMID 39919333, 2025). "It was found that age, SBP, FPG, DBP, ALB, LDL-C, hs-CRP, and OC were positively correlated with osteoporosis, while negative correlations were observed with BMI, LYM, ALB, TP, TG, HDL-C, SCr, UA, and VitD." (PMID 38475712, 2024). "Unsurprisingly, we found that the CRP level, an inflammatory reactive cytokine, was higher in patients with osteoporosis than in those without osteoporosis." (PMID 37614952, 2023). "We did not found the associations between disease activities and osteoporosis risk in the present study including severe skin tightness, dcSSc subset, internal organ involvement, or inflammatory markers (ESR, CRP)." (PMID 33941800, 2021). "CRP levels were not different between patients with normal bone density, osteopenia or osteoporosis." (PMID 30323223, 2018). "C-reactive protein level (odds ratio (OR) 3.8 and OR 6) and glucocorticoid use (OR 1.5 and OR 1.7) were associated with a high risk of osteoporotic fracture based on FRAX without BMD and osteoporosis diagnosed according to the WHO criteria." (PMID 35628957, 2022). "Furthermore, women with osteoporosis at two or more anatomical sites had higher CRP levels than women without osteoporosis." (PMID 32156247, 2020). "Our study also demonstrated that the CRP level is significantly different between patients with normal BMD and patients with osteoporosis, indicating that inflammation may be involved in the pathogenesis of osteoporosis." (PMID 29768330, 2018). "However, disease activity-associated factors (ESR, CRP, and DAS28-ESR), RF and ACPA showed no independent association with osteoporosis." (PMID 26912147, 2016). "However, because tests to determine CRP level are relatively available and inexpensive, this parameter may worth considering first for detection of the existence and severity of inflammation in COPD to predict disease outcome and the possibility of extra-pulmonary comorbidity such as osteoporosis." (PMID 29340241, 2018).